ACE (angiotensin I converting enzyme)
Diseases named in the same sentence as ACE in open-access papers (continued):
Sharing a sentence is not in itself a finding about the gene and the disease.
Hypertension (continued). "Moreover, a number of ACE-inhibiting peptides derived from natural food materials have been successfully developed as effective alternatives to synthetic drugs for the prevention of hypertension in a safer manner." (PMID 35159478, 2022). "Therefore, when compared to other antihypertensive drugs, ACE inhibitors and ARBs may be better choices to treat hypertension in this population." (PMID 35075396, 2022). "The upregulation of ACE and ACE2 enzymes, and of AT1 receptors, among a downregulation of AT2, Mas and MrgD receptors, have an impact in NADPH oxidase expression, and thus, influence the redox status and contribute to vascular remodeling and fibrosis associated with hypertension." (PMID 35163158, 2022). "Likewise, fucoxanthin isolated from the Sargassum wightii (Greville) species demonstrated an in vitro antioxidant activity and suppression of ACE, suggesting that it might be used as a dietary additive to treat hypertension." (PMID 35464014, 2022). "Our previous work revealed that dimethyl fumarate administration during pregnancy protected adult offspring from the hypertension programmed by prenatal dexamethasone plus a postnatal high-fat diet (which are relevant to the downregulated mRNA expression of renin, angiotensinogen, ACE, and AT1R)." (PMID 35955421, 2022). "Once these PC patients had survived the cancer at least that long and were in remission, other causes of death had become more common and patients treated with ACE inhibitors likely experienced greater risk of death from non-PC causes due to their diabetes, hypertension, or other indications." (PMID 35130875, 2022). "Therefore, inhibitors of ACE activity can be used to manage hypertension." (PMID 36499176, 2022). "Therefore, inhibition of ACE has become a modern therapeutic target to treat hypertension." (PMID 36547528, 2022). "In both studies, the levels of ACE and Ang II decreased, which could indicate that the antihypertensive mechanism of foxtail millet consists of inhibiting the activity of the ACE in the serum of subjects with slight hypertension." (PMID 37430980, 2022). "Furthermore, treating the hypertension with ACE inhibitors results in upregulation of the angiotensin-converting enzyme II (ACE-II), which could facilitate infection with COVID-19." (PMID 35889751, 2022). "Hypertension is typically managed solely with pharmacotherapy such as angiotensin-converting-enzyme (ACE) inhibitors and beta-blockers, however, surgical correction of neurologic structural disorders such as cervical nerve root impingement may also play a role." (PMID 35855243, 2022). "Since both medication classes are primarily prescribed for patients with hypertensive disease, this negative causal effect further underlines the importance of ACE inhibitors in controlling COVID-19 severe illness (diuretics: ORIVW = 0.47, PIVW = 2.66E-15; RAAS: ORIVW = 0.36, PIVW = 1.87E-17)." (PMID 36583016, 2022). "Therefore, seaweed has the potential to inhibit ACE-1 similar to other known synthetic drugs including Captopril® and Enalapril and could potentially serve as an alternative treatment for high blood pressure." (PMID 35206049, 2022). "Additionally, it has been previously reported a sex-specific effect of ACE gene I/D polymorphism on other CMR parameters, such as blood pressure and hypertension; however, our study only reported significant sex*genotype interactions in MFO, the main variable regarding metabolic flexibility." (PMID 33810312, 2021). "Inhibition of ACE in COVID-19 patients with hypertension reported reduced disease severity with downregulation of IL-6 and higher T cell numbers, suggesting the exaggerated activation of Ang-II/AT1R axis may contribute towards the uncontrolled cytokine response leading to ALD." (PMID 33632295, 2021).
Hypertension (continued). "In addition, hypertension, which is a long-term complication of diabetes and also a risk factor for cardiovascular disease (CVD), can be well managed through the proper inhibition of angiotensin I-converting enzyme (ACE)." (PMID 34281584, 2021). "Therefore, ACE inhibition is key in controlling high blood pressure, and ACE inhibitory peptides could be used as a nutraceutical strategy for hypertension management and prevention." (PMID 34574209, 2021). "However, its assurance of the safety of calcium-channel blockers and the other two drugs (diuretics and ACE-inhibitors) in terms of GI bleeding may still be relevant to the clinical prescription of antihypertensive drugs for patients with hypertension." (PMID 34793552, 2021). "Another study of approximately 5000 patients with hypertension and type 2 diabetes demonstrated reductions in mean plasma glucose in those treated with nebivolol as monotherapy (21.4%), although 48.4% were also being treated with an ACE inhibitor or angiotensin receptor blocker (ARB)." (PMID 34603773, 2021). "Therefore, ACE inhibitors and ARBs that are capable of reducing the production of inflammatory cytokines are potential candidate drugs for treatment of patients with COVID-19 and preexisting hypertension." (PMID 34912542, 2021). "ACE inhibitors,angiotensin receptor blockers (ARBs), beta-blockers, Ca- antagonists, and diuretics have successfully reduced blood pressure and cardiovascular events in randomized clinical trials, making them the first-line recommended therapy for hypertension." (PMID 34567170, 2021). "In addition to acting as ACE inhibitors for the treatment of hypertension, these peptides have other probiotic properties, such as antioxidant and anti-inflammatory properties, that are important for the prevention and treatment of hypertension." (PMID 33920763, 2021). "We hypothesized that Sodium Thiosulfate improves cardiac disease in an experimental hypertension model and sought to investigate its cardioprotective effects by direct comparison to the ACE-inhibitor lisinopril, alone and in combination, using a rat model of chronic nitric oxide (NO) deficiency." (PMID 33935760, 2021). "For now, there is no need to replace ACE inhibitors or AT1R blockers with other drugs (during the treatment of arterial hypertension) during the COVID-19 pandemic for fear of a higher risk of SARS-CoV-2 infection and a more life-threatening course of the disease." (PMID 33925881, 2021). "Therefore, AT1R antagonists and ACE inhibitors are frequently used for the control of hypertension." (PMID 34440554, 2021). "In summary, our observations demonstrated that quinoa protein is a promising natural source of ACE inhibitory peptides and is capable of lowering the blood pressure in SHRs, in which fecal microbiota has experienced a significant alteration, and towards that in non-hypertension rats." (PMID 34371955, 2021). "One hypothesis postulates that ACE inhibitors and/or ARBs, taken by approximately 65% of our participants with hypertension, may mediate changes in baseline inflammation or in ACE2 receptor expression or affinity through the renin-angiotensin-aldosterone system." (PMID 34871308, 2021). "This idea had important practical consequences since it lead to propose that Angiotensin receptor blockers (ARB) and ACE inhibitors (ACE-I) commonly used to treat hypertension may favour viral propagation since they upregulate the viral receptor ACE2, and should be discontinued." (PMID 34322518, 2021). "Recent studies have reported that the application of ACE inhibitors can induce a marked increase in ACE2 expression, which means that ACEIs/ARBs would increase the risk of COVID-19 infection and disease aggravation of COVID-19 in hypertension and diabetes patients receiving these drugs." (PMID 33850192, 2021). "Also, eggplant inhibits ACE activity and thereby can reduce high blood pressure." (PMID 34094022, 2021).
Hypertension (continued). "However, ACE inhibitors—which are standard therapeutics for the treatment of high blood pressure, and may have a vital role in viral infections and pneumonia —have not yet been shown to inhibit ACE2." (PMID 32982616, 2021). "Moreover, phycobiliproteins, intensely fluorescent proteins isolated from the red alga P. palmata, could be used in the prevention of hypertension due to their great angiotensin-converting enzyme (ACE) inhibitory activity." (PMID 32660153, 2020). "If CO-induced ̇OH production is susceptible to ACE inhibitors and AT1R antagonists, which are widely used for the treatment of hypertension and its complications with high safety, then the RAS may be a novel therapeutic target for brain damage due to CO poisoning." (PMID 32054947, 2020). "Moreover, additional BP lowering could be achieved when BTTQ was administered on top of ACE inhibitor lisinopril, a current standard of care in the treatment of hypertension." (PMID 33013477, 2020). "Interestingly, common hypertension medication modulation, including use of renin inhibitors, ACE inhibitors, and Ang-II receptor blockers (ARBs) may play a role in modulation of ACE2, based on previous studies." (PMID 32501190, 2020). "Owing to the role of ACE2 in SARS-CoV2 pathogenicity, it has been speculated that medical conditions, i.e., hypertension, and/or drugs, i.e., ACE inhibitors and angiotensin receptor blockers, known to influence ACE2 density could alter the fate of SARS-CoV-2 infection." (PMID 33195436, 2020). "Moreover, additional blood pressure lowering of about 22 mmHg could be achieved when BTTQ was administered on top of ACE inhibitor lisinopril, a current standard of care in the treatment of hypertension." (PMID 33013477, 2020). "Recent studies have suggested that patients with hypertension and diabetes treated with ACE inhibitors (ACEIs) or angiotensin receptor blockers have a higher risk of COVID‐19 infection as these drugs could upregulate ACE2, motivating the study of ACE2 modulation by drugs in current clinical use." (PMID 32729248, 2020). "The observed down-regulation of ACE2 by SARS-CoV-2 could suppress that increase in ACE2 levels mediated by ACE-Is and ARBs, thus counteracting their beneficial effects on hypertension and CVD, and explaining the poorer clinical outcome observed when these comorbidities are present." (PMID 32575076, 2020). "Since ischemic stress associated with arteriosclerosis triggers ROS production in cases of hypertension, antihypertensive agents such as angiotensin-converting enzyme (ACE) inhibitors and angiotensin II type 1 receptor blockers (ARBs) may be useful for early intervention." (PMID 32922259, 2020). "Conversely, the pharmacological blockade of either angiotensin converting enzyme (ACE) or angiotensin II (AngII) type 1 (AT1) receptor during late nephrogenesis (postnatal days 2–14) impair renal maturation and is associated with the development of hypertension later in life." (PMID 32982785, 2020). "Furthermore, the activation of the ACE/Ang II/AT1R axis also causes no hypertensive disorders, such as cerebral hypoperfusion and ischemic injury." (PMID 32184813, 2020). "Thus, one might expect maternal DMF therapy to block the classical ACE-Ang II-AT1R axis of the RAS in a way that opposes the development of hypertension in DEX+HF offspring rats." (PMID 31416234, 2019). "For example, with an indication of heath failure diuretics, beta-blockers, ACE inhibitors, angiotensin receptor blockers, calcium channel blockers and aldosterone antagonists are the first-line medications recommended for the effective management of hypertension." (PMID 31671730, 2019). "Therefore, our study aimed to establish the role of ACE and AGT gene polymorphisms in the mechanisms behind the development of oxidative stress in patients with concomitant chronic obstructive pulmonary disease and hypertension." (PMID 32025262, 2019).
Hypertension (continued). "However, the increase in oxidative stress parameters was observed to be the most significant in patients with chronic obstructive pulmonary disease + hypertension and with I/I genotype of the ACE gene, which was due to their lowest values in virtually healthy individuals." (PMID 32025262, 2019). "Therefore, the increased adipose tissue mass observed in MetS may possibly increase aldosterone which in turn stimulate the function of RAS resulting the increase ACE activity and finally increase angiotensin II resulting in hypertension." (PMID 31827683, 2019). "Thus, inhibition of ACE has become the main target in the treatment of hypertension." (PMID 31842519, 2019). "Therefore, ACE inhibition is a major target in the prevention and treatment of hypertension." (PMID 31683604, 2019). "Thus, the results of the present study indicate the potential of stone fish protein hydrolysates as a suitable raw material for the industrial production of ACE-inhibitory peptides which could be used in effective treatment of hypertension." (PMID 31145747, 2019). "Therefore, screening and developing new ACE inhibitors from A. decursiva could be beneficial in the treatment of cardiovascular diseases such as hypertension." (PMID 31683604, 2019). "Thus, the present study demonstrated the potential of Todarodes pacificus as a suitable raw material for the industrial production of ACE-inhibitory peptides, which could be used to effectively treat hypertension." (PMID 31454889, 2019). "Therefore, inhibiting ACE is among the major therapeutic methods for treating hypertension." (PMID 31717478, 2019). "Therefore, ACE could be a potential therapeutic target in regulating the conversion of angiotensin I to angiotensin II and eventually controlling hypertension." (PMID 30875817, 2019). "Hence, ACE inhibition plays a physiological role in the treatment of hypertension." (PMID 31216636, 2019). "Thus, intrarenal Ang II formation stimulated by the induction of AGT, renin and ACE may contribute to sodium and water retention and high blood pressure." (PMID 31680980, 2019). "AA patients with essential hypertension have repeatedly been shown to be more salt sensitive and more responsive to diuretics, with less activation of the circulatory renin-angiotensin-aldosterone system, and less sensitivity to ACE inhibition or angiotensin receptor blockade." (PMID 31532792, 2019). "Interestingly, despite this increased energy and macronutrient intake, patients in the higher fiber intake group also had lower BMI, superior metabolic control of diabetes, and inferior use of medications to treat diabetes (insulin) and hypertension (ACE inhibitors)." (PMID 29694634, 2018). "Thus, ACE inhibitors and ARBs may have the greater potential to improve hypertension for women than men, particularly in those with obesity." (PMID 30364090, 2018). "However, despite there being several studies suggesting a positive impact of phlorotannins on hypertension based on their ability to act as ACE inhibitors or due to their antioxidant properties, limited in vivo experiments using rodent models of hypertension are available to confirm this impact." (PMID 30060542, 2018). "Recent data suggest that patients with PV and hypertension who are treated with angiotensin-converting enzyme (ACE) inhibitors may require less cytoreductive treatment to control hematocrit levels compared with those who are treated with other antihypertensive agents." (PMID 29728092, 2018). "This high ACE inhibition potential of flavonoid fraction of Coriandrum sativum certifies that no other phytoconstituents including tannins, alkaloids, and steroids but only the flavonoids of this plant may manage hypertension through ACE inhibition mode of action." (PMID 30581531, 2018).
Hypertension (continued). "Croatian and Slovenian medication lists contain several additional combinations, ACE inhibitors, diuretics, calcium channel blockers, beta blockers, and statins, the display of which would decrease the transparency of basic therapeutic groups of medicine for treatment of hypertension." (PMID 29167787, 2017). "However, recent data indicates that ACE2 has an opposing effect to that of ACE which could have novel implications regarding the role of RAS in hypertension and cardiovascular diseases." (PMID 28423630, 2017). "Moreover, the ACE gene, with the absence of the I allele has been related to higher ACE circulation levels as well as lower hypertension." (PMID 28336767, 2017). "However, after adjusting for age and gender, drinking and smoking status, hypertension, use of ACE inhibitors or ARBs and MS components (BMI, BP, TG, HDL-C), both elevated FPG and HbA1c levels showed an independent relationship with an increased risk for hyperfiltration." (PMID 28610620, 2017). "However, after adjusting for age, gender, drinking and smoking status, hypertension, control of diabetes and hypertension and use of angiotensin-converting enzyme (ACE) inhibitors or angiotensin receptor blockers (ARBs), this negative association of MS and eGFR remained intact." (PMID 28610620, 2017). "Thus, we compared the effects of blocking the RAAS by the ACE inhibitor ramipril to reducing noradrenergic sympathetic vascular tone by the alpha 1-adrenoceptor blocker doxazosin in patients with uncomplicated mild-to-moderate hypertension." (PMID 27885499, 2017). "Thus, ACE inhibitory peptides can be used for anti-hypertension." (PMID 29160816, 2017). "It was demonstrated that phenolic acids have an inhibitory effect on α-amylase, α-glucosidase associated with type 2 diabetes and the angiotensin converting enzyme (ACE), which suggest that it may provide a new method for the treatment of hyperglycemia and hypertension in some ways." (PMID 28880243, 2017). "In addition, we observed a significant increase in ACE activity and aldosterone levels, which may have contributed directly to the onset of hypertension." (PMID 29234376, 2017). "Many synthetic ACEi drugs such as captopril, benazepril and enlapril are currently widely used in hypertension and heart failure treatment, whereas, these classic ACEi exert side effects, there will be a huge commercial interest in new, safe chemicals with ACE-inhibiting efficiency." (PMID 28827527, 2017). "Therefore, ACE inhibitors have been widely prescribed for patients with both diabetic and non-diabetic symptoms to prevent angiotensin II production during the treatment of hypertension related to metabolic syndrome." (PMID 29065451, 2017). "Thus, depending on the respective genotype, it might be worth considering an alternative drug for hypertension medication with respect to efficacy as well as side effects possibly induced by a shift in ACE substrate specificity." (PMID 27120469, 2016). "Hypertension treatment with diuretics, ACE inhibitors, and calcium channels blockers were more prevalent in tinnitus patients, suggesting that an eventual ototoxicity of these drugs may be involved in tinnitus pathophysiology, a hypothesis that should be evaluated in further studies." (PMID 27761128, 2016). "Indeed, ACE inhibition lowered blood pressure in 7-month-old mice exposed to DDT to a greater extent than observed in the vehicle group, demonstrating that a primary cause of hypertension induced by perinatal DDT exposure is an over-activated RAS." (PMID 27325568, 2016). "More specifically, African‐American populations, in whom low‐renin, volume‐expansive hypertension is a common comorbid cardiovascular condition, the use of augmenters of ACE‐inhibitor action is encouraged to reduce the very high doses of ACE inhibitors otherwise required." (PMID 26993743, 2016).